CD86 (CD86 molecule)
Diseases named in the same sentence as CD86 in open-access papers (continued):
Sharing a sentence is not in itself a finding about the gene and the disease.
co-infection (5 papers, 2014 to 2022). "We found a minor depletion of CD80+CD86+ cells following GAS infection (p = 0.1), whereas co-infection caused a significantly increased proportion of this population when compared to uninfected controls." (PMID 36365071, 2022). "Both CD11chigh and CD11int cells displayed a significant reduction in CD86 surface expression in co-infected compared to those from M. tuberculosis infected mice, indicating that P. yoelii co-infection interfered with cell activation." (PMID 26913029, 2016). "Similarly, co-infection triggered a minor overexpression of CD86 that was short of reaching statistical significance due to a high within-group variance (p = 0.067, compared to uninfected)." (PMID 36365071, 2022). "In contrast, a reduced maturation of DCs was observed upon co-infection with HIV-C and Chlamydia (HIV-C/Chlam-DCs) and this maturation was comparable to that when iDCs were exposed to HIV-C only (CD83—left panel, CD86—middle panel, HLA-DR—right panel)." (PMID 31178863, 2019). "Moreover, reduced expression of CD86 on both CD11chigh and CD11cint cells as observed 21 days after co-infection was no longer apparent at this late time-point." (PMID 26913029, 2016). "In addition, CD86 upregulation in human immunodeficiency virus as well as simian immunodeficiency virus co-infection of dendritic cells in vitro was IFN-β but not IFN-α-dependent." (PMID 24472094, 2014). "Another study with HCV genotype 1 mono-infected individuals did not report elevated CD86 expression in SVRs, suggesting that HIV-1 co-infection could be the possible cause of high baseline maturation state of pDCs." (PMID 25705565, 2014).
dengue (5 papers, 2013 to 2021). "In this study we examined the expression level of TLR2, 3, 4 and 9 and of the co-stimulatory molecules CD80 and CD86 in dengue patients experiencing distinct disease manifestations." (PMID 23469297, 2013). "Furthermore, the expression of CD80 and CD86 was altered in mDCs and CD86 in pDCs of severe dengue cases." (PMID 23469297, 2013). "In addition, expression of CD80 and CD86 was altered in DCs of severe dengue cases." (PMID 23469297, 2013). "Therefore, B cells from dengue patients were stained with anti-Ki-67 and anti-CD69/anti-CD86, two activation markers, and with anti-NS3 to identify infected cells." (PMID 33643283, 2020). "Here, the percentage of CD69+ and CD86+ naïve B cells remained significantly lower in B cells from dengue patients with respect to healthy donors even upon stimulation via BCR and TLR (median CD69+, 16.9 vs 40.2%; P < 0.05) (median CD86+, 26.5 vs 49.2%; P < 0.05)." (PMID 31736948, 2019).
eosinophilia (5 papers, 2007 to 2023). "The percentage of Cd45+ F4/80+ CD86+ cells (M1-like macrophages) was significantly elevated in lung tissue of neutrophilia-dominant mice (5.56%) when compared with control mice (2.01%) or eosinophilia-dominant mice (2.20%)." (PMID 37898756, 2023). "Asai-Tajiri and colleagues managed to experimentally attenuate allergic inflammation, including eosinophilia, IgE and TH2 cytokine expression in lung upon OVA-exposure, by blocking CD86 locally with siRNA." (PMID 27513955, 2016). "Eosinophilia in curcumin-treated mice was markedly reduced, co-stimulatory molecule expression (CD80, CD86, and OX40L) on antigen-presenting cells was decreased, and expression of MMP-9, OAT, and TSLP genes was also attenuated." (PMID 17254346, 2007). "Regarding in vivo models, a previous study showed that intranasal administration of anti-CD86 mAb markedly reduced AHR, IgE production, and airway eosinophilia in OVA-sensitized/challenged mice whereas the treatment with anti-CD80 reduced airway eosinophilia alone." (PMID 25344652, 2014).
Hyperglycemia (5 papers, 2021 to 2025). An increased concentration of glucose in the blood. "M2-like macrophages reacted to prolonged hyperglycemia only on day 7 by increasing expression of HLA-DR and CD86." (PMID 40821781, 2025). "As can be seen from the flowcytometry data, hyperglycemia caused a rapid and robust decrease in the number of CD11b, CD11b+F4/80, CD11b+CD206, CD11b+CD86, and CD11b+MHCII double-positive cells in the lacrimal gland." (PMID 39749321, 2024). "The expression of CD83 and CD86 were significantly upregulated in splenic CD11c+ DCs derived from mice with hyperglycemia." (PMID 35062863, 2022). "Moreover, no significant decrease in CD11b+CD206 double-positive cells was noted, whereas a reduction in CD11b+CD86 double-positive cells was observed at all the 3 tested time points after hyperglycemia." (PMID 39749321, 2024). "Hence, the administration of a slow-releasing H2S donor, GYY-4137, downregulated the expression of M1 markers (i.e., iNOS, CD11c, and CD86) elicited by LPS under our in vitro approach of hyperglycaemia." (PMID 37335394, 2023). "Furthermore, hyperglycemia did not modulate the number of CD11b+CD86 double-positive proinflammatory macrophages in the conjunctiva." (PMID 39749321, 2024).
inflammatory bowel disease (5 papers, 2017 to 2025). A spectrum of small and large bowel inflammatory diseases of unknown etiology. "The DC surface receptor costimulatory molecules CD86, CD80, CD83, and CD40 generate important signals for stimulating naive T cell differentiation and may inhibit oral tolerance in not only IDDM but also inflammatory bowel disease (IBD) and multiple sclerosis." (PMID 28396662, 2017). "In inflammatory bowel disease, activated DCs could release the inflammatory cytokines such as IL-6, IL-12 and tumor necrosis factor (TNF-α) by up-regulating the pattern recognition receptors [Toll-like receptor (TLR) 2 and TLR4], MHC class II molecules, and costimulatory molecules (CD40 and CD86)." (PMID 37670381, 2023). "Moreover, IECs isolated from patients with inflammatory bowel disease (IBD) expressed MHC II, CD80 and CD86 and were found capable of inducing CD4 T cell proliferation and IFNγ secretion." (PMID 31316504, 2019).
Insulin resistance (5 papers, 2013 to 2022). Increased resistance towards insulin, that is, diminished effectiveness of insulin in reducing blood glucose levels. "Regardless of insulin resistance, the two groups of women with morbid obesity showed upregulation of LYPD8 and downregulation of a greater number of genes, such as REG1B, GKN2, LPL, PNLIPRP2, FKBP5, and CD86, that are related to responses to bacterial stimuli and antimicrobial activity." (PMID 35625760, 2022).
lymph node metastasis (5 papers, 2020 to 2025). "Our univariate analysis found that in CRC patients, lower differentiation, advanced TNM stage, and lymph node metastasis were associated with higher expression of CD163+ TAM and lower expression of CD86+ TAM." (PMID 41395618, 2025). "CA-199 (p = 0.014), lymph node metastasis (p = 0.029), tumor multiplicity (p = 0.007) and CD86+/CD206+ TAMs model (p = 0.003) were utilized to construct the OS nomogram." (PMID 32002338, 2020). "Multivariable analyses revealed that apart from CA-199, lymph node metastasis and tumor multiplicity, CD86+/CD206+ TAMs model remained to be the independent prognostic indicator for both OS (p = 0.003) and RFS (p = 0.005)." (PMID 32002338, 2020). "On the other hand, lymph node metastasis (p < 0.001), tumor multiplicity (p = 0.002) and CD86+/CD206+ TAMs model (p = 0.005) were selected to build the RFS nomogram." (PMID 32002338, 2020). "Furthermore, a relationship between clinical stage and Breslow thickness (<2mm/≥2mm), tumor ulceration, lymph node metastasis, and CD80 and CD86 expression was also identified." (PMID 37614091, 2024). "The expression of CD86 was higher in patients who did not have lymph node metastasis." (PMID 37614091, 2024).
meningioma (5 papers, 2013 to 2025). A generally slow growing tumor attached to the dura mater. "Six antigens were exclusively found in the immunopeptidome of WHO grade I meningiomas (CAPN14, KIR2DS4, TMM44, ECD, CD86, and RFWD3), whereas WHO grade I and III meningiomas showed only one antigen in common (KLC2)." (PMID 37368072, 2023). "In accordance with higher infiltrations of immune and stromal cells and higher expression of classic immune checkpoints: CD86, PDCD1, and LAIR1, cluster 1 meningiomas might be more sensitive to immunotherapy." (PMID 41050085, 2025).
mesothelioma (5 papers, 2015 to 2022). A usually malignant and aggressive neoplasm of the mesothelium which is often associated with exposure to asbestos. "The upregulation of CD86 and downregulation of CD1a expression suggests that mesothelioma tumor cells induce partial iMoDC maturation." (PMID 25886502, 2015). "The in vitro studies showed that mesothelioma cells and/or their factors initiated an early, but incomplete, maturation of iMoDCs, as evidenced by increased CD86 and reduced CD1a expression." (PMID 25886502, 2015).
myocarditis (5 papers, 2021 to 2024). Myocarditis is a condition that is characterized by inflammation of the heart muscle (myocardium). "CD86 is also associated with myocarditis and gallbladder squamous cell carcinoma." (PMID 35682950, 2022). "The higher expression of CD86 in DCs from myocarditis patients suggests that in this condition, DCs present a higher immunogenic status increasing their ability to prime T cells." (PMID 35265721, 2022). "Interestingly, we found that myocarditis patients showed higher percentages of CD86 positive myeloid DCs compared with healthy controls (p = 0.01)." (PMID 35265721, 2022). "Diseases related to CD86 include acute myocarditis and myocarditis." (PMID 34950700, 2021). "The dominant role of reparative macrophages in the later phase of DOX-induced myocardial inflammation supports our finding that, after eight weeks of DOX treatment, the expression of the anti-inflammatory macrophage marker CD163 but not CD86 was significantly increased compared to CTRL." (PMID 38247537, 2024).
sarcoma (5 papers, 2017 to 2024). A usually aggressive malignant neoplasm of the soft tissue or bone. "Sunitinib treatment induced a significant upregulation of co-stimulation molecules CD80 and CD86 in both sarcoma cell lines (p < 0.01 and p < 0.0001, respectively) when compared to DCs loaded with untreated sarcoma cells." (PMID 33717062, 2021). "The double treatment also strongly decreased the number of TAM displaying the M2 marker CD206, which heavily infiltrate 3-MCA sarcoma from untreated mice, whereas the few CD86+ TAM present were unaffected by the therapy." (PMID 28978047, 2017). "We assessed a panel of pediatric sarcoma cell lines, including OS (SJSA-1, U2OS), RMS (RD, RH30) and EwS (A673, TC32, TC71 and SKNMC) for their basal expression of the immunogenic surface markers CD86, CD83, PD-L1, ICAM-1, MHC-I and MHC-II in comparison to healthy donor-derived PBMCs." (PMID 39723214, 2024).
thymoma (5 papers, 2014 to 2024). A neoplasm arising from the epithelial cells of the thymus. "Strikingly, in THCA and THYM (thymoma), NEIL3 was significantly associated with more than 20 immune checkpoint genes, such as CD86, ICOS, TNFSF4, and CD48, implying its role in regulating the tumor immune microenvironment." (PMID 36612106, 2022). "In order to study the IS in a setting resembling physiology, we set Jurkat T cells to interact with TCS-CD86, a mouse thymoma cell line modified to express a membrane bound anti-CD3 antibody fragment and the CD86 costimulatory molecule." (PMID 35095913, 2021). "In Cox regression analysis, the results revealed that CD86 expression was significantly associated with survival rates in five cancer types, i.e., cervical squamous cell carcinoma and endocervical adenocarcinoma (CESC), LGG, skin cutaneous melanoma (SKCM), thymoma (THYM) and uveal melanoma (UVM)." (PMID 33954112, 2021).
ulcerative colitis (5 papers, 2014 to 2024). An inflammatory bowel disease involving the mucosal surface of the large intestine and rectum. "Notably, the expression pattern of CD86 and CD14 in mucosal cells as observed in the organ culture model resembles that in intestinal inflammation in vivo (ulcerative colitis)." (PMID 24841635, 2014).
ZIKV infection (5 papers, 2017 to 2025). "ZIKV infection was associated with increased expression of IBA1 and CD86, indicative of predominant M1 microglial activation." (PMID 40821819, 2025). "Our results showed that intermediate-activated monocytes, in response to ZIKV infection, exhibited adhesion (CD11b+ CD11c+) properties and expressed co-stimulatory molecules (CD80+ CD86+)." (PMID 38247836, 2024). "To determine the ability of ZIKV infection to program DCs, we measured cell surface expression of co-stimulatory (CD80, CD86, and CD40) and MHC class II molecules at 48hpi with all four ZIKV strains." (PMID 28152048, 2017). "In contrast, B cells displayed only twofold higher levels of CD86 following ZIKV infection, whereas no CD86 upregulation at all was noticed in monocytes and mDCs." (PMID 32415086, 2020). "Our findings suggest that, during ZIKV infection, human monocytes differentiate from the classical to the intermediate phenotype and that they enter an activated state that is maintained up to 96 h p.i., with detectable levels of CD11b, CD11c, CD80, CD86, and viral E/NS1 proteins." (PMID 38247836, 2024).
Alzheimer disease (4 papers, 2020 to 2023). A progressive, neurodegenerative disease characterized by loss of function and death of nerve cells in several areas of the brain leading to loss of cognitive function such as memory and language. "Our findings showed a significant decrease (p = 0.049) in the expression levels of CD86 (MFI 579.3) in classical monocytes of Alzheimer’s disease patients compared to those with other dementias (MFI 597.1)." (PMID 37445910, 2023). "Neuroinflammation induced by hypoxia activates M1 microglia and reduces M2 microglia by determining CD86 and Arginase-1 expression in Alzheimer’s disease." (PMID 37166426, 2023).
autoimmune hepatitis (4 papers, 2021 to 2026). Hepatitis caused by autoantibodies. "Another study focusing on autoimmune hepatitis (AIH)/PBC variants found that the levels of expression of soluble LAG3, TIM3, CD86, and CD25 in AIH were higher and could be differentiated from PBC." (PMID 39859319, 2025). "Unlike CD4+ T cells binding to liver cell MHC-II molecules to form TCR-CD3-peptide-MHC-II complexes, which are later removed from liver cells in autoimmune hepatitis, MHC-IIlo/-CD86+ DCs cannot efficiently contact CD4+ T cells." (PMID 34220808, 2021).
Burkitt lymphoma (4 papers, 2021 to 2024). A rare form of malignant mature B-cell non-Hodgkin lymphoma. "To establish a range of target cells for our experiments, we analyzed the surface expression of CD80 and CD86 on four DLBCL and one Burkitt lymphoma cell line." (PMID 38340727, 2024).
chronic myelogenous leukemia (4 papers, 2008 to 2024). "When co-cultured with chronic myeloid leukemia (CML) cell lysates, the expression of co-stimulatory molecules (CD40, CD80 and CD86) and antigen-presenting molecule HLA-DR on Vγ9Vδ2 T cells could be strongly up-regulated." (PMID 33664732, 2020).
cutaneous melanoma (4 papers, 2020 to 2022). A primary melanoma arising from atypical melanocytes in the skin. "The key immune checkpoints including BTLA, CD86, CD244, and PDCD1 are recognized as predictors of sentinel lymph node metastasis in cutaneous melanoma." (PMID 35069935, 2022).
dementia (4 papers, 2020 to 2023). Loss of intellectual abilities interfering with an individual's social and occupational functions. "The phenotypic transformation from homeostatic microglia towards reactive microglia in dementia pathologies is associated with TREM2, HLA-DRA, ENTPD1 (CD39), CD80 (B7-1), CD86 (B7-2), CCR5, CD274, ITGAX (CD11c), TIMD4 and MRC1." (PMID 33113879, 2020). "Moreover, CD56bright NK cells in MS donors expressed higher levels of adhesion molecules (CD49d, CD54 and CD31), ligand PDL1, costimulatory molecule CD86, and lower levels of CD45RA and T-bet relative to control and dementia cases." (PMID 35536009, 2022).
diffuse large B-cell lymphoma (4 papers, 2020 to 2025). "Previous studies demonstrated that the loss of STAT1 activation or expression was found in malignant cells derived from various tumors, while the loss of CD86 expression resulted in a decrease in tumor-infiltrating T lymphocytes in diffuse B-cell large-cell lymphoma." (PMID 32549786, 2020). "Importantly, macrophages expressing high levels of CD163 and CD86 have been observed in diffuse large B cell lymphoma, suggesting that the NLC phenotype may be seen in other B-cell malignancies and that AHCC may be effective there as well." (PMID 38140397, 2023).
experimental autoimmune encephalomyelitis (4 papers, 2014 to 2023). An autoimmune demyelinating disease of the central nervous system that is produced experimentally in animals by the injection of homogenized brain or spinal cord in Freund's adjuvant. "Increased expression of co-stimulatory molecules has usually been associated with an immune activating phenotype of APCs, but recently expression of B7 (CD80/CD86) on murine B cells was shown to be central to regulation of CD4+CD25high Tregs in experimental autoimmune encephalomyelitis." (PMID 25401487, 2014).
infarction (4 papers, 2020 to 2025). A localised pathological necrosis of tissue resulting from obstruction of the blood supply usually by a thrombus, an embolus, or vascular torsion. "Our findings suggest that complete deletion of PKM2 in mice leads to chronic pro‐inflammatory signaling, exacerbated inflammation, and sustained CD86+ macrophage activation after infarction, which correlates with worse patient outcomes." (PMID 39761962, 2025). "Similarly, ox‐LDL could further induce the expression of CD83 and CD86 on the basis of Ang II (P < .05), indicating that a high‐fat internal environment can further stimulate the inflammatory mechanism in vivo and aggravate myocardial inflammatory response after infarction." (PMID 32073735, 2020).
liver cancer (4 papers, 2023 to 2025). An epithelial or non-epithelial malignant neoplasm that arises from the liver. "In addition, the glycolysis intensity was significantly correlated with the expression of PD-L1 in CD86+ macrophages in liver cancer and the mechanism involves HIF-1α-dependent elevation of PKM2." (PMID 37434177, 2023). "We detected the expression of CYPJ, CD86 (a marker for M1 TAMs), CD163 (a marker for M2 TAMs), CD8 (a marker for CD8+ T cell), and EpCAM (a marker for tumor cells) in tissues from liver cancer patients using the mIHC method." (PMID 40520002, 2025). "Expressions of PD-L1, CD86, and CD206 were positively correlated with the infiltration level of immune cells in liver cancer, while the expression of PD-L1 was positively correlated with the degree of tumor differentiation." (PMID 37306737, 2023). "Bioinformatics analysis found that PD-L1, CD86, and CD206 were underexpressed in various tumor tissues including liver cancer, while the present immunohistochemical detection found that PD-L1, CD86, and CD206 were overexpressed in liver cancer tissues." (PMID 37306737, 2023). "The results of the pathological stage analysis revealed that the patients with a higher proportion of CD86+CYPJ+ (M1 TAMs) macrophages or CD8+CYPJ+ T cells exhibited a lower pathological grade, indicating that CYPJ acted as a protective factor against liver cancer." (PMID 40520002, 2025). "Therefore, the in-depth study of PD-L1, CD86, and CD206 could not only find biomarkers for prognosis assessment of patients with liver cancer, but also provide new therapeutic targets for the immunotherapy of the patients." (PMID 37306737, 2023).
lung adenocarcinoma (4 papers, 2021 to 2024). A carcinoma that arises from the lung and is characterized by the presence of malignant glandular epithelial cells. "We found that the expression of CD28, CD80, andCD86 was markedly reduced, suggesting that PSMB6 may decrease their expression to reduce the binding between CD80/CD86 and CD28, ultimately leading to immune evasion in lung adenocarcinoma cells." (PMID 39507618, 2024).